BDNF (brain derived neurotrophic factor)
Diseases named in the same sentence as BDNF in open-access papers (continued):
Sharing a sentence is not in itself a finding about the gene and the disease.
depression (continued). "Our goal was to explore the BDNF/TrkB neurotrophic activity of OC and subsequently assess its potential for modulating neuroinflammatory response using human neuroblastoma cells (SH-SY5Y cells) and an in vivo model of depression induced by lipopolysaccharide (LPS)-mediated inflammation." (PMID 38835076, 2024). "Furthermore, a meta-analysis of biomarkers in bipolar depression showed a negative correlation between blood levels of BDNF and depression severity score, supporting the role of BDNF in the depressive phase of bipolar depression." (PMID 38500272, 2024). "Studies with T2DM (Type 2 diabetes mellitus) individuals lacking depression revealed a significant decrease in BDNF concentrations, indicating that BDNF may be connected to depression in T2DM patients." (PMID 37287291, 2024). "Therefore, it appears that on one side, there are antioxidant systems and growth factors promoting plasticity, such as Nrf2–HO-1, BDNF, Akt, TrkB, and CREB, which are protective from depression and, on the other side, GSK-3β and NF-κB, which promote depressive behaviour." (PMID 37107192, 2023). "The BDNF pathway might be disturbed in IBD, linking it to sleep disorders and depression." (PMID 36984890, 2023). "Therefore, exercise can ameliorate depression by upregulating PGC-1α, FNDC5, and BDNF expression." (PMID 37239191, 2023). "In the pain-depression dyad model, we evaluated immobile time, neurotransmitter levels, interleukin-1 (IL-1β) and tumor necrosis factor-α (TNF-α) levels, and the expression of mRNA of brain-derived neurotrophic factor (BDNF) and tryptophan hydroxylase 2 (Tph2)." (PMID 38259687, 2023). "Additionally, participants who suffered from depression had slightly higher odds for low BDNF values, compared to non-depressed subjects." (PMID 37012351, 2023). "Thus, therapeutics that promote the close correlation between dentate neurogenesis and BDNF, as seen under the GALR2 and Y1R agonist combination, maybe the key to preventing or curing depression." (PMID 36599082, 2023). "However, the study did not include the methylation analysis of BDNF gene promoter regions which seemed most relevant in predicting depression in the studies performed on adults." (PMID 34590201, 2023). "Furthermore, prevalence of low-BDNF values was slightly higher in subjects with depression compared to non-depressed individuals." (PMID 37012351, 2023). "Thus, early childhood stress is linked to the miR-16 upregulation and subsequent downregulation of the brain-derived neurotrophic factor (BDNF) gene in the hippocampus, in which depression-like behaviors were induced by maternal deprivation or chronic unpredictable stress in rats." (PMID 37111391, 2023). "Furthermore, BDNF levels were lower in the patients with depression compared to non-depressed subjects, and positively affected by performing physical training in the early but not in the long term." (PMID 37719764, 2023). "In patients with incidence of depression, its development during the follow-up period appears to be related to the severity of CVD and is associated with more severe treatments and longer hospital stays but not with low serum BDNF levels." (PMID 37895349, 2023). "Our findings highlight BDNF-TrkB system as the molecular target of ELS-induced spatial memory deficits and provide translational evidence for the intervention at this system in the treatment of cognitive deficits in stress-related psychiatric disorders, such as major depressive disorder." (PMID 37225683, 2023). "Additionally, several studies have found lower serum BDNF levels in patients with depression, compared to non-depressed individuals." (PMID 37631295, 2023). "Antioxidant systems and plasticity-promoting molecules, such as those in the Nrf2–HO-1, BDNF–TrkB, and cyclic AMP–CREB pathways, could protect from depression, while glycogen synthase kinase-3β and nuclear factor κB oppose these actions, thus increasing depressive-like behaviours." (PMID 37107192, 2023).
depression (continued). "In addition to examining the relationships between anxiety and depression in MHD patients and serum levels of BDNF, NT-3, and 5-HT, this research sought to determine the factors that may influence these conditions." (PMID 37750080, 2023). "Post-mortem studies have not supported a similar BDNF reduction in late-life depression compared to dementia, and no study has yet investigated whether basal BDNF level predicts response to antidepressants." (PMID 36621964, 2023). "Taken together, BDNF may be a suitable marker for highly stressed conditions, i.e., a marker of depression, but may not be suitable for the evaluation of stress levels at an early stage." (PMID 36834565, 2023). "In humans, one study found that subjects who respond to ketamine treatment for depression show higher levels of BDNF (24 h after administration) than non-responders and that there was a negative correlation between BDNF levels and Montgomery-Asberg Depression Rating Scale (MADRS) score." (PMID 36527355, 2023). "Even though increased serum BDNF after acute ECT may indicate that ECT corrected the BDNF changes in depression, several studies have reported a lack of any significant changes in serum BDNF concentrations after ECT." (PMID 37174977, 2023). "This leads us to propose that an intriguing link between the effects on BDNF and the CAR may be due to improving hippocampal functional integrity and related to hippocampal neurogenesis and likely related to its positive effects on well‐being and depression." (PMID 36178333, 2023). "In a chronic unpredictable mild stress (CUMS) depression mouse model, Clostridium butyricum was found to attenuate depressive-like behavior by increasing 5-HT, Glucagon-like peptide-1 (GLP-1), and Glucagon-like peptide 1 receptor (GLP-1R) concentrations and upregulating BDNF expression." (PMID 37759312, 2023). "Moreover, we highlight the role of BDNF in other psychiatric OSA sequelae (e.g., depression)." (PMID 36768132, 2023). "BDNF has also been extensively studied in the context of mental health; its decreased levels were observed in psychological disorders, such as dementia or depression, although those changes are not specific." (PMID 36984890, 2023). "Investigating the biological mechanisms underlining this bidirectional relationship, some animal and human studies have hypothesised that BDNF might play a mediating role in the onset of one of these two diseases because lower serum BDNF levels were observed in patients of both CVD and depression." (PMID 37895349, 2023). "This mismatch is confirmed by the analysis of the correlation between BDNF decline and stroke severity: All of the included studies reported significantly higher NIHSS scores in patients who had lower BDNF levels at diagnosis and reported depression in the post-stroke period." (PMID 37895349, 2023). "Moreover, there is a negative correlation between serum BDNF stored in platelets and depression in humans." (PMID 36831706, 2023). "Overall, exercise can promote the expression of BDNF and CREB by increasing SIRT1 expression in the hippocampus, and moreover, it can activate the SIRT1/IGF-1/GAP-43 and SYN signaling pathways to increase the volume of SVZ and SGZ, improving neurogenesis, and eventually relieving depression." (PMID 37239191, 2023). "We wanted to determine whether epigenetic changes, such as DNA methylation patterns of the candidate genes (BDNF, COMT, and SLC6A4) in peripheral blood, correlate with the duration and acute severity of anxiety and depression symptoms measured with clinical scales (BDI-II, HAM-A, and IDS-C)." (PMID 37754245, 2023). "In our sample, BDNF levels did not correlate with depression severity." (PMID 34904800, 2023). "However, as of 2022, there are a few studies on this subject; one shows that BDNF bears no relation to depression in women with moderate or severe OSA." (PMID 36768132, 2023).
depression (continued). "The commonly reported biomarkers of depression include serum corticosterone levels (cortisol levels in humans) to assess the involvement of the HPA axis, pro-inflammatory cytokines (TNF-alpha, IL-1, and IL-6), brain-derived neurotrophic factor (BDNF), and neurotransmitters (5-HT, DA, NE, and GABA)." (PMID 36986112, 2023). "Furthermore, a plethora of studies showed that the PTEN/AKT/mTOR or BDNF/synaptophysin pathway was not changed in a variety of depression models compared to that of the control group." (PMID 36969556, 2023). "Since the first scientific publication recording differences in serum concentrations of brain-derived neurotrophic factor (BDNF) between depressed individuals and healthy controls, the hypothesis of imbalance in the neurotrophin system in depression has also been investigated." (PMID 36559251, 2022). "Since this relation is not so evident in BD patients, some authors suggest that BDNF levels might be a tool used to distinguish depression in the course of BD from MDD." (PMID 35448545, 2022). "BDNF-TrkB signaling-mediated upregulation of Narp in the hippocampus may play a key role in the antidepressant-like effect of (2R,6R)-HNK in the CRS model of depression." (PMID 35291971, 2022). "The lower mean of BDNF level in our FM group could be related to the higher depression scores in the FM patients rather than the NP group." (PMID 35501732, 2022). "However, some studies show that the level of BDNF under the influence of physical activity, especially in patients with depression, does not change significantly." (PMID 35546921, 2022). "Our study also confirms the significantly lower levels of BDNF in patients with stroke than the healthy controls, patients with the clinical diagnosis of depression to non-depressed patients and significantly higher levels of BDNF in patients who do moderate to severe physical training." (PMID 35287688, 2022). "A contradictory study found that BDNF is significantly decreased in the luteal phase compared to the control, and decreased BDNF levels are often accompanied by negative emotions such as anxiety and depression." (PMID 36699021, 2022). "Although BDNF may have an important involvement in the pathophysiological mechanism of depression, it does not seem to be a reliable indicator of functional outcome in the general population." (PMID 35510613, 2022). "Depression is accompanied by the changes in the levels of inflammatory and trophic factors, including interleukins (IL-1beta, IL-2, IL-6), interferon alpha (IFN-alpha), tumor necrosis factor alpha (TNF-alpha), C-reactive protein (CRP), and brain derived neurotrophic factor (BDNF)." (PMID 35455388, 2022). "Further, the expression of BDNF is regulated via cyclic adenosine monophosphate response element-binding protein (CREB), and the phosphorylated cyclic adenosine monophosphate response element-binding protein (pCREB) level in the hippocampus was one of the pathogenesis of depression." (PMID 36761172, 2022). "Furthermore, Xiaoyao pills has antioxidant and neuroprotective effects on both cortical and hippocampal regions, which can improve depression-like behavior and oxidative stress of olfactory bulb excised rats by activating PIK3CA-AKT1-NFE2L2 BDNF signaling pathway." (PMID 36569324, 2022). "Rodents fed high-fat high-sugar foods rather than high-fat foods only have a reduction of BDNF levels, which could be a causal link between SSB consumption and depression." (PMID 35215425, 2022). "There are also no data on whether and to what extent brain BDNF levels change in severe and prolonged depression." (PMID 35563389, 2022). "In FST-induced depression in rats, paeoniflorin can alleviate both the hyperactivity of the HPA axis and oxidative damage, increase plasma and hippocampal monoamine neurotransmitters and brain-derived neurotrophic factor (BDNF) levels, and promote gastrointestinal movement." (PMID 36408279, 2022).
depression (continued). "Therefore, low serum BDNF level is involved in the pathogenesis of both MetS and neurodegenerative diseases (NDD) like Huntington’s disease, Parkinson’s disease, Alzheimer’s disease, and depression." (PMID 36185667, 2022). "The present study aimed to investigate whether the BDNF, VEGF, S100B, and IGF-1 in serum levels can be helpful to identify MDD in knee OA patients and to evaluate the potential relationship of these neurotrophins with depression and pain assessments." (PMID 36386998, 2022). "Moreover, alterations in miR-132 and miR-124 values in non-treated and citalopram-treated patients with depression have shown that enhancement of both miRNAs increases plasma BDNF values." (PMID 35916975, 2022). "One explanation for the reduced levels of both neurotrophins (NGF and BDNF) in our study could be that a subgroup of the EM and CM patients had concomitant undiagnosed depression and therefore were not receiving antidepressants." (PMID 34991456, 2022). "Brain-derived neurotrophic factor (BDNF), a topic neurotrophic factor of intensive research in the mammalian brain, contributing to the maintenance and survival of neurons and activity-dependent regulation of synapse number and function, is integral to the pathophysiology of depression." (PMID 35814253, 2022). "Molecular and behavioral studies deepened the role of neurotrophic/growth factors (such as BDNF, NGF, IGF-1, and FGF-2) in depression, demonstrating that the levels of those factors were reduced in animal models and in depressed and/or stressed patients (“neurotrophic hypothesis of depression”)." (PMID 35886944, 2022). "In a rat model of chronic, unpredictable, stress-induced depression, memantine treatment was shown to have an antidepressant-like effect by preventing hippocampus mitochondrial dysfunction and memory impairment via the upregulation of the CREB/BDNF signalling pathway." (PMID 36362262, 2022). "Therefore, modulation in the BDNF/CREB/ERK signaling cascade and inhibition through crocin might provide further insights into the importance of behavioral changes during the depression." (PMID 35408474, 2022). "In addition, FA can selectively regulate BDNF expression by regulating H3K27me3 in astrocytes rather than microglia, which is important for the progression of depression." (PMID 35197855, 2022). "Although the BDNF decreased in chronic stress and depression, the acute increase is not good news." (PMID 35646186, 2022). "Though neuroinflammation and reduced BDNF levels were only coincident and not causally linked in IBD models, impaired BDNF signaling might be triggered by neuroinflammation and contribute to depression and anxiety in IBD." (PMID 36232412, 2022). "Notably, majority of the preexisting studies evaluated the effect of various antidepressants on BDNF level in patients with depression without pain." (PMID 35501732, 2022). "In addition, when BDNF was selectively deleted in the forebrain of inducible knockout mice, no basal alterations in depression-related behavior were highlighted." (PMID 36430921, 2022). "Furthermore, treatment targeting neuronal C/EBPβ signaling, assisted by an anti-inflammatory agent or oral BDNF mimetic compound such as 7,8-DHF, may ameliorate the onset and progression of both depression and diabetes in the general population." (PMID 36578534, 2022). "However, reduced plasma or serum levels of BDNF are not specific to depression, and the same results have been observed in other mental disorders, such as schizophrenia, bipolar disorder, and Alzheimer's disease." (PMID 36186850, 2022). "However, in people with depression, the reduction in serum and plasma BDNF levels seem to be independent of platelet reactivity, suggesting that other cells are involved in this modulation." (PMID 35911513, 2022).
depression (continued). "Furthermore, NF-kB regulates neurogenesis and synaptic plasticity in the nervous system by interacting with the brain-derived neurotrophic factor (BDNF), which is a cornerstone of the neurotrophic hypothesis of depression." (PMID 36012250, 2022). "Therefore, the increase in BDNF in the hippocampus of TB animals could be related to the beneficial effect of CUR on memory and the decrease in depression-like behavior in this model." (PMID 35216083, 2022). "Besides, it has been reported that BDNF is required for the anxiolytic and antidepressant actions of selective serotonin reuptake inhibitors (SSRI), which are the first line of pharmacological interventions for anxiety and depression treatment." (PMID 35898162, 2022). "Candidate gene studies have long been performed, but their positive findings are now being questioned, as 18 well-studied MDD candidate genes (e.g., BDNF, COMT, HTR2A, MAOA) have failed to exhibit any associations with depression phenotypes in a much larger sample." (PMID 36233781, 2022). "As such, treatments that increase BDNF levels, including vagal nerve stimulation, may not be an asset to treat comorbid depression and RA." (PMID 35330475, 2022). "Nevertheless, the role of BDNF in depression pathogenesis is not univocal." (PMID 36430921, 2022). "Brain-derived neurotrophic factor (BDNF)-tropomyosin receptor kinase B (TrkB) pathway, mitogen-activated protein kinase (MAPK) pathway, glycogen synthase kinase-3 (GSK-3) pathway, toll-like receptor 4 (TLR4) pathway, etc. are involved in the pathological process of depression." (PMID 35923544, 2022). "When heterozygous Bdnf null (Bdnf+/−) mice were employed to assess BDNF’s role in the antidepressant response, a ~50% reduction in BDNF levels did not impact depression-related behavior per se, but the antidepressant imipramine was ineffective in the forced swim test." (PMID 36430921, 2022). "Similarly, lower BDNF and proBDNF levels may define OSA phenotypes with intensified symptoms of depression." (PMID 36498709, 2022). "Notably, serum level of BDNF showed a non-significant difference between two pain groups (FM and NP) after adjustment for depression, disease severity and pain intensity." (PMID 35501732, 2022). "In an ovariectomized Wistar rat model of depression induced by CUMS, vitamin D3 (5 mg/kg for 4 weeks; s.c.)treatment was able to reverse depression-like behaviors in the sucrose preference test and the forced swimming test by increasing BDNF and NT-3/NT-4 levels in the hippocampus." (PMID 35806075, 2022). "Moreover, the BDNF knockout mice show obvious depression such as lack of pleasure and lower exploration competence." (PMID 34984950, 2022). "The results of this study may suggest that BDNF levels do not have a role in the effects of psychotherapy in the treatment of depression, which contrasts with the results of other studies." (PMID 36672535, 2022). "At the same time, it could be interesting to study the BDNF concentration in the brain of the victims of suicide, since not all the people who commit suicide have a diagnosis of depressive disorder or other psychiatric conditions." (PMID 36611538, 2022). "It is hypothesized that MNA cannot effectively resist the inflammatory factors produced in depression disorder or limit the effect of BDNF regulation in the PFC." (PMID 35370823, 2022). "Moreover, NFkβ causes an increase in cytoplasmic CREB levels in BD patients, which is of interest as the activity of BDNF against ROS is mediated via CREB transcription, and BDNF levels are lower in mania than in depression and lower in BD patients compared to controls." (PMID 34295268, 2021). "The promoter of BDNF IV is the most well-characterized promoter that responds to stress in depression pathogenesis, as rodent models of depression exposed to social-defeat stress showed decreased mRNA levels of total BDNF and BDNF IV but neither BDNF transcripts in response to restraint stress." (PMID 34577589, 2021).